CYP11A1 (cytochrome P450 family 11 subfamily A member 1)
Description:
A cytochrome P450 monooxygenase that catalyzes the side-chain hydroxylation and cleavage of cholesterol to pregnenolone, the precursor of most steroid hormones. Catalyzes three sequential oxidation reactions of cholesterol, namely the hydroxylation at C22 followed with the hydroxylation at C20 to yield 20R,22R-hydroxycholesterol that is further cleaved between C20 and C22 to yield the C21-steroid pregnenolone and 4-methylpentanal. Mechanistically, uses molecular oxygen inserting one oxygen atom into a substrate and reducing the second into a water molecule. Two electrons are provided by NADPH via a two-protein mitochondrial transfer system comprising flavoprotein FDXR (adrenodoxin/ferredoxin reductase) and nonheme iron-sulfur protein FDX1 or FDX2 (adrenodoxin/ferredoxin).
Synonyms: CYP11A; P450SCC; CYPXIA1
Tractability: Small molecule: an approved drug acts on it; a structure with a bound ligand is known; it has a high-quality binding pocket; it belongs to a druggable protein family. Antibody: UniProt places it where antibodies can reach, with high confidence.
Target class: Cytochrome P450 family 11A; Cytochrome P450; Cytochrome P450 family 11; Enzyme; Cytochrome P450 11A1
Gene: Protein-coding gene on chromosome 15 (74,337,746 to 74,367,680, reverse strand). Ensembl gene ENSG00000140459.
Subcellular location: Mitochondrion inner membrane
Pathways (Reactome):
Metabolism: Endogenous sterols; Pregnenolone biosynthesis
Disease: Defective CYP11A1 causes AICSR
Gene Ontology:
Molecular function: cholesterol monooxygenase (side-chain-cleaving) activity; heme binding; protein binding; iron ion binding; monooxygenase activity; oxidoreductase activity, acting on paired donors, with incorporation or reduction of molecular oxygen; oxidoreductase activity, acting on paired donors, with incorporation or reduction of molecular oxygen, reduced iron-sulfur protein as one donor, and incorporation of one atom of oxygen; steroid hydroxylase activity
Biological process: C21-steroid hormone biosynthetic process; cholesterol metabolic process; steroid hormone biosynthetic process; cellular response to peptide hormone stimulus; cortisol metabolic process; glucocorticoid biosynthetic process; sterol metabolic process; vitamin D metabolic process; C21-steroid hormone metabolic process
Cellular component: mitochondrion; mitochondrial inner membrane; mitochondrial matrix
Genetic constraint (gnomAD): Loss-of-function variants: 29 observed, 56.62 expected, observed/expected ratio (o/e) 0.51, 90% interval 0.38 to 0.7. The upper end of that interval is the gene's LOEUF score, 0.7, which puts it in group 2 of 6, group 1 being the genes least tolerant of losing a copy. Missense variants: 578 observed, 716.79 expected, observed/expected ratio (o/e) 0.81, 90% interval 0.75 to 0.86. Synonymous variants: 245 observed, 277.46 expected, observed/expected ratio (o/e) 0.88, 90% interval 0.8 to 0.98.
Homologues: Orthologues: chimpanzee CYP11A1 (99% identical), macaque CYP11A1 (98% identical), dog CYP11A1 (80% identical), pig CYP11A1 (79% identical), rabbit CYP11A1 (78% identical), rat Cyp11a1 (76% identical), mouse Cyp11a1 (75% identical), tropical clawed frog cyp11a1 (48% identical), zebrafish cyp11a1.2 (46% identical), zebrafish cyp11a1.1 (45% identical). Paralogues in human: CYP11B2 (37% identical), CYP11B1 (36% identical).
Diseases named in the same sentence as CYP11A1 in open-access papers:
CYP11A1 is named in the same sentence as 146 diseases in open-access papers, as found by Europe PMC text mining. Sharing a sentence is not in itself a finding about the gene and the disease. The quoted sentences say what the papers report.
polycystic ovary syndrome (21 papers, 2012 to 2025). A disorder that manifests as multiple cysts on the ovaries. "The objective of this study was to investigate the allele frequencies of polymorphisms in genes CYP11A1 rs4886595 and CYP11A1 rs4887139 that are responsible for the steroidogenesis mechanism in polycystic ovary syndrome patients and control females." (PMID 39045925, 2024). "Related studies indicated that the SNP‐derived mutations of CYP11A1 were closely related to reproduction and to the susceptibility to polycystic ovary syndrome, which can cause either chronic ovulation or anovulation (i.e., lack of ovulation)." (PMID 33780162, 2021). "The CYP11A1 gene has long been linked to the pathogenesis of polycystic ovary syndrome and the major mechanism attributed is related to the abnormal androgen metabolism." (PMID 29163791, 2017). "They examined the segregation of CYP11A1 in 20 families and performed association studies in premenopausal women with polycystic ovaries and matched control women from a similar ethnic background." (PMID 27769286, 2016). "We hypothesized that obesity leads to the upregulation of CYP11A1 in G05 cell subsets causing hyperandrogenemia, resulting in anovulation and infertility." (PMID 38956667, 2024). "This might be assumed that genetic polymorphisms in the CYP11A1 prompter may influence gene expression and may result in a condition related to hormonal changes, such as polycystic ovarian syndrome." (PMID 35205347, 2022). "Polymorphisms of CYP11A1 have been detected as potential markers in different hormone-dependent diseases, including breast cancer, polycystic ovary syndrome (PCOS), prostate cancer, and endometrial cancer." (PMID 22606018, 2012). "The percentage of CYP11A1 rs4887139 and CYP11A1 rs4886595 heterozygosity in the polycystic ovary syndrome and control groups." (PMID 39045925, 2024). "Notably, the interaction between LONP1 and cytochrome P450 family 11 subfamily A member 1 has been implicated in polycystic ovary syndrome (PCOS), and pharmacological interventions such as artemisinin have been shown to alleviate PCOS phenotypes by enhancing this interaction." (PMID 41256733, 2025). "Based on the case history discussed so far, CYP11A1 might be considered as a biomarker, which is most likely correlated with infertility in polycystic ovary syndrome." (PMID 35205347, 2022). "A transmission disequilibrium test (TDT) in affected siblings with hyperandrogenemia and PCOS-related traits predicted a strong association of follistatin, a nominal association of CYP11A1 gene, and a strong genetic association D19S884 allelic marker around INSR gene with PCOS." (PMID 34563259, 2021). "Abnormal CYP11A1 expression may therefore affect steroid levels, which are closely related to various diseases, such as polycystic ovary syndrome (PCOS), breast cancer, and other hormone-related disorders." (PMID 35002603, 2021). "In polycystic ovaries, there seems to be an alteration in the CYP11A1 gene expression." (PMID 27769286, 2016). "Their results demonstrated that differences in expression of CYP11A1 could account for variation in androgen production in women who have polycystic ovaries." (PMID 27769286, 2016). "Other studies demonstrated decreased expression of FSHR and CYP11A1 and increased expression of CYP19A1, STAR, HSD3B2 and INHBA in polycystic ovary granulosa cells compared to controls." (PMID 36768772, 2023). "Jakimiuket al studied the genetic basis of receptors in granulosa and theca cells of polycystic ovaries and reported higher mRNA expression levels of LH receptor (LHR), StAR, CYP11A1, and CYP17A1." (PMID 27769286, 2016). "Additionally, oxidative stress appears to also induce key steroidogenic molecules in TC, namely, CYP11A1, CYP17A1, 3-β-HSD, and StAR, favoring hyperandrogenemia." (PMID 25763405, 2014).
polycystic ovary syndrome (continued). "Patients with polycystic ovary syndrome may have follicle development impairment due to elevated levels of estrogen and pregnenolone in follicular fluid; the mechanism is in part mediated by changes in the expression of HSD17B1, CYP19A1, and CYP11A1 in FF exosomes." (PMID 36210808, 2022).
Adrenal insufficiency (15 papers, 2007 to 2026). Insufficient production of steroid hormones (primarily cortisol) by the adrenal glands. "More recently, partial loss-of-function of CYP11A1 has been reported in children with delayed-onset adrenal insufficiency and hypospadias or glucocorticoid insufficiency alone." (PMID 30620006, 2019). "In this report, we describe a patient with adrenal insufficiency, hypospadias, and skin hyperpigmentation who was found to have a novel c.425+1G>A variant in trans with the p.E314K variant in CYP11A1." (PMID 29178636, 2017). "In conclusion, the compound heterozygous presence of the c.425+1G>A and p.(E314K) variants in CYP11A1 found in this patient, explain the reported primary adrenal insufficiency diagnosis." (PMID 29178636, 2017). "CYP11A1 deficiency results in complete or partial adrenal insufficiency with a wide range of clinical manifestations." (PMID 29178636, 2017). "Compound heterozygosity for the CYP11A1 gene with a known pathogenic variant in one allele and a novel splice site mutation in the second allele is most probably responsible for congenital adrenal insufficiency with 46,XY sex reversal." (PMID 34281122, 2021). "This is analogous to partial loss-of-function mutations in CYP11A1, which give rise to adrenal insufficiency in humans; the proteins may retain 30–40% of wild-type activity this is insufficient to maintain normal cortisol production." (PMID 29046340, 2018). "The clinical differentials of sex reversal with adrenal insufficiency include P450scc deficiency due to mutations in CYP11A1 gene, Smith-Lemli-Opitz syndrome (DHCR7 gene), NR5A1 (SF1) mutation-related sex reversal, CYP17 and 3-beta hydroxysteroid dehydrogenase deficiency (HSD3B2 gene)." (PMID 23748066, 2013). "Among these were the associations of KHDC3L with ovarian insufficiency, RFX6 with diarrheal-type intestinal dysfunction, CYP11A1 (also known as cholesterol side chain cleavage enzyme) with adrenal insufficiency (AI), and SOX10 with vitiligo." (PMID 32410729, 2020). "Mutations in genes related to steroid biosynthesis (such as CYP11A1, CYP17A1, HSD3B2, HSD17B3, and StAR) will lead to androgen synthesis disorders with adrenal insufficiency besides the SRD5A2 gene mutation which results in the insufficient transformation of dihydrotestosterone from testosterone." (PMID 40247401, 2025). "Autoantibodies against steroid 21-hydroxylase (CYP21A2), steroid 17α-hydroxylase (CYP17A1), and cytochrome P450 family 11 subfamily A member 1 (CYP11A1) have been detected in many APS-1 patients with Addison’s disease years before adrenal insufficiency became clinically apparent." (PMID 30002654, 2018). "Some of these are localized to certain geographical areas (eg, p.R451W in CYP11A1 in eastern Turkey, c.IVS3ds+1delG in MRAP in western Turkey), which could lead to focused cost-effective clinical genetic testing for patients and families at risk of adrenal insufficiency in these regions." (PMID 26523528, 2016).
congenital adrenal hyperplasia (15 papers, 2016 to 2025). Congenital adrenal hyperplasia (CAH) is an inherited endocrine disorder caused by a steroidogenic enzyme deficiency that is characterized by adrenal insufficiency and variable degrees of hyper or hypo androgyny manifestations, depending of the type and the severity of the disease. "For example, studies using Star, Cyp11a1, and Hsd3b2 mutant mice have delineated critical steps in steroidogenesis that mirror the enzymatic defects seen in human congenital adrenal hyperplasia (CAH)." (PMID 41357796, 2025). "Furthermore, these findings match with our earlier observations showing an evident adrenal hyperplasia accompanied by an enhanced steroidogenic machinery since StAR, CYP11A1, CYP11B1, and 11β-HSD1 expression are increased in this period." (PMID 31998227, 2019). "Congenital adrenal hyperplasia (CAH) refers to a group of seven monogenic adrenal disorders, caused by pathological variants in genes coding for enzymes in the adrenal steroidogenic pathway: CYP21A2, CYP11B1, CYP17A1, HSD3B2, STAR, CYP11A1, and POR." (PMID 41450580, 2025). "Congenital adrenal hyperplasia (CAH) is a group of autosomal recessive disorders caused by pathogenic variants identified in seven genes (CYP21A2, CYP11B1, CYP17A1, HSD3B2, StAR, POR, and CYP11A1) involved in the steroidogenesis pathway." (PMID 39451515, 2024).
breast carcinoma (14 papers, 2010 to 2025). "Studies have shown CYP11A1, which can hydroxylate the side-chain of vitamin D3 at carbons 17, 20, 22, and 23, are related to susceptibility to breast cancer." (PMID 36419007, 2022). "Acrylamide interacted statistically significantly with 2 SNPs in CYP11A1: rs2959008 and rs7173655; acrylamide intake was associated with a decreased ER+ breast cancer risk in women who were homozygous for the wild type of these alleles." (PMID 29445914, 2019). "In a previous study, we genotyped six SNPs in the estrogen biosynthesis gene CYP11A1, and three variants (rs2279357, rs2959003, and rs2959008) were identified as associated with susceptibility to breast cancer." (PMID 25689428, 2015). "We have previously investigated the polymorphisms in CYP11A1 and found that rs2279357, rs2959003, and rs2959008 were related to breast cancer risk." (PMID 25689428, 2015). "Here, we investigated the associations between single nucleotide polymorphisms (SNPs) in CYP11A1 and breast cancer among Han Chinese women in Guangdong province, South China." (PMID 22606018, 2012). "Our results suggest that polymorphisms of CYP11A1 are related to breast cancer susceptibility in Han Chinese women of South China." (PMID 22606018, 2012). "In summary, our results showed that rs2959008 and rs2279357 of the CYP11A1 gene were significantly associated with breast cancer susceptibility among Guangdong Han Chinese women, and the interaction of these two SNPs was associated with elevated risk." (PMID 22606018, 2012). "In this study, the associations between single nucleotide polymorphisms (SNPs) in CYP11A1 and breast cancer susceptibility were examined." (PMID 22606018, 2012). "Interestingly, certain CYP11A1 polymorphisms have also been associated with an increased risk to develop breast cancer." (PMID 36861295, 2023). "Besides, six tagging SNPs were examined in the Han Chinese Women Study to prove an association between CYP11A1 and breast cancer." (PMID 33780162, 2021). "The interaction with SNPs in CYP1B1 and CYP11A1 suggests that acrylamide may influence ER+ breast cancer risk through sex hormone pathways." (PMID 29445914, 2019). "In our previous study, three SNPs, rs2279357, rs2959003, and rs2959008, in CYP11A1 were validated to be associated with breast cancer risk (OR = 1.558, 95% CI = 1.092–2.222, p = 0.014; OR = 0.668, 95% CI = 0.460–0.971, p = 0.034 and OR = 0.669, 95% CI = 0.452–0.991, p = 0.045)." (PMID 25689428, 2015). "Elevated expression of PRMT1 and CYP11A1 was observed in highly metastatic human breast cancer cell lines and knockdown of these genes through RNA interference suppressed the motility and invasion of MDA-MB-231 cells without affecting their viability." (PMID 34919051, 2021). "Similar results were obtained using the EO771 breast cancer orthotopic tumor model: deletion of Cyp11a1 in T cells restricted dissemination to and nodule formation in the lung." (PMID 32680985, 2020). "After adjustment for multiple testing, this study showed statistically significant interactions between rs1056827 in CYP1B1, rs2959008 and rs7173655 in CYP11A1, the deletion of GSTT1, and rs1052133 in hOGG1 and acrylamide intake for ER+ breast cancer risk." (PMID 29445914, 2019). "Among the results for 57 SNPs and 2 gene deletions, rs1056827 in CYP1B1, rs2959008 and rs7173655 in CYP11A1, the GSTT1 gene deletion, and rs1052133 in hOGG1 showed a statistically significant interaction with acrylamide intake for ER+ breast cancer risk." (PMID 29445914, 2019). "Six SNPs in CYP11A1 were genotyped using the MassARRAY IPLEX platform in 530 breast cancer patients and 546 healthy controls." (PMID 22606018, 2012). "If true, the interactions between acrylamide and HSD3B SNPs for ovarian cancer and between acrylamide and the CYP1B1 and CYP11A1 SNPs for breast cancer in the current study give some indications that acrylamide may interfere with progesterone metabolism." (PMID 29445914, 2019).
breast carcinoma (continued). "Observation of mast cell expression of Cyp11a1 in breast cancer never been reported." (PMID 40287432, 2025). "Whereas StAR and key steroidogenic enzyme genes evaluated (CYP11A1, HSD3B, CYP17A1, CYP19A1, and HSD17B) were altered to varying levels in these hormone responsive cancers, amplification of the StAR gene was correlated with poor overall survival of patients afflicted with breast cancer." (PMID 31060224, 2019).